TRBV17 (T cell receptor beta variable 17 (non-functional))
Description:
Probable non-functional open reading frame (ORF) of V region of the variable domain of T cell receptor (TR) beta chain. Non-functional ORF generally cannot participate in the synthesis of a productive T cell receptor (TR) chain due to altered V-(D)-J or switch recombination and/or splicing site (at mRNA level) and/or conserved amino acid change (protein level). Alpha-beta T cell receptors are antigen specific receptors which are essential to the immune response and are present on the cell surface of T lymphocytes. Recognize peptide-major histocompatibility (MH) (pMH) complexes that are displayed by antigen presenting cells (APC), a prerequisite for efficient T cell adaptive immunity against pathogens. Binding of alpha-beta TR to pMH complex initiates TR-CD3 clustering on the cell surface and intracellular activation of LCK that phosphorylates the ITAM motifs of CD3G, CD3D, CD3E and CD247 enabling the recruitment of ZAP70. In turn ZAP70 phosphorylates LAT, which recruits numerous signaling molecules to form the LAT signalosome. The LAT signalosome propagates signal branching to three major signaling pathways, the calcium, the mitogen-activated protein kinase (MAPK) kinase and the nuclear factor NF-kappa-B (NF-kB) pathways, leading to the mobilization of transcription factors that are critical for gene expression and essential for T cell growth and differentiation. The T cell repertoire is generated in the thymus, by V-(D)-J rearrangement. This repertoire is then shaped by intrathymic selection events to generate a peripheral T cell pool of self-MH restricted, non-autoaggressive T cells. Post-thymic interaction of alpha-beta TR with the pMH complexes shapes TR structural and functional avidity.
Synonyms: TCRBV17S1; TCRBV26S1P
Gene: T-cell receptor variable (V) gene on chromosome 7 (142,601,628 to 142,602,360, forward strand). Ensembl gene ENSG00000277880.
Subcellular location: Cell membrane
Gene Ontology:
Biological process: cell surface receptor signaling pathway
Cellular component: plasma membrane
Homologues: Orthologues: chimpanzee TRBV17 (82% identical). Paralogues in human: TRBV7-3 (56% identical), TRBV12-3 (55% identical), TRBV12-4 (55% identical), TRBV12-5 (54% identical), TRBV11-1 (53% identical), TRBV11-2 (52% identical), TRBV7-6 (52% identical), TRBV14 (51% identical), TRBV7-2 (51% identical), TRBV11-3 (50% identical), TRBV7-7 (50% identical), TRBV7-9 (50% identical), and 39 more.
Diseases named in the same sentence as TRBV17 in open-access papers:
TRBV17 is named in the same sentence as 1 disease in open-access papers, as found by Europe PMC text mining. Sharing a sentence is not in itself a finding about the gene and the disease.
TRBV17 shares sentences with these, for which no sentence is quoted: infection (1 paper).